SNORD13 (small nucleolar RNA, C/D box 13)
Synonyms: U13; RNU13; SNORD13A
Gene: Small nucleolar RNA gene on chromosome 8 (33,513,475 to 33,513,578, forward strand). Ensembl gene ENSG00000239039.
Gene Ontology:
Biological process: RNA processing
Cellular component: nucleolus
Homologues: Orthologues: chimpanzee SNORD13 (97% identical), macaque SNORD13 (91% identical). Paralogues in human: SNORD13P3 (95% identical), SNORD13P1 (89% identical), SNORD13E (88% identical), SNORD13D (88% identical).
Diseases named in the same sentence as SNORD13 in open-access papers:
SNORD13 is named in the same sentence as 2 diseases in open-access papers, as found by Europe PMC text mining. Sharing a sentence is not in itself a finding about the gene and the disease. The quoted sentences say what the papers report.
Huntington disease (1 paper, 2024). Huntington disease (HD) is a rare neurodegenerative disorder of the central nervous system characterized by unwanted choreatic movements, behavioral and psychiatric disturbances and dementia. "SNORD13, for instance, is specifically associated with Huntington’s disease (HD), involved in genomic activities related to HD pathophysiology, with increases plasma levels indicating disease progression." (PMID 39000310, 2024).
SNORD13 also shares sentences with these, for which no sentence is quoted: osteoarthritis (1 paper).